ADAMTS13 (ADAM metallopeptidase with thrombospondin type 1 motif 13)
Diseases named in the same sentence as ADAMTS13 in open-access papers (continued):
Sharing a sentence is not in itself a finding about the gene and the disease.
viral infection (6 papers, 2021 to 2025). "Although a causal relationship remains to be elucidated, viral infections are a known trigger for secondary or immune TTP, with proposed mechanisms including both direct endothelial injury and creation of ADAMTS13 autoantibodies." (PMID 35997402, 2022). "Our rationale to measure ADAMTS13 levels was based on reports of ADAMTS13 antigen and activity decreases in other infections, including bacterial sepsis, and in viral infection-induced secondary TTP due to ADAMTS13 specific IgG inhibitor production." (PMID 35087853, 2021).
antiphospholipid syndrome (5 papers, 2010 to 2025). A disorder caused by the presence of autoantibodies directed against phospholipids, causing a hypercoaguable state, which may result in blood clots, stroke, heart attack, and in women, significant pregnancy-related complications, including miscarriage and still birth. "Women with obstetric anti-phospholipid syndrome can develop placental diseases, such as PE, a diagnosis associated with reduced ADAMTS13 levels." (PMID 40362344, 2025). "Failure of TMA to improve in the postpartum period or occurring at this time, with negative ADAMTS13 and antiphospholipid antibody syndrome (APLAS) serologies should favor the diagnosis of p-aHUS." (PMID 37942411, 2023). "Indeed, idiopathic TMA with detectable ADAMTS13 activity share features of atypical HUS and antiphospholipid syndrome and probably includes various subsets of diseases with distinct pathophysiological mechanisms that require now to be clearly identified." (PMID 20436664, 2010).
Cerebral ischemia (5 papers, 2017 to 2025). Restriction of arterial blood supply to the brain associated with insufficient oxygenation to support the metabolic requirements of the tissue. "This contrasts with findings from reperfusion-based models such as cerebral ischemia, where ADAMTS13 deficiency led to enhanced neutrophil-driven injury, suggesting that its role in ischemic inflammation may depend on the specific pathophysiological context." (PMID 41009700, 2025). "Plasma levels of ADAMTS-13 were reduced in the early phase after aSAH in patients with delayed cerebral ischemia." (PMID 34064048, 2021). "Thus, ADAMTS-13 has been identified as a potential biomarker for delayed cerebral ischemia after aSAH." (PMID 34064048, 2021). "Thus, reduced ADAMTS13 activity, as shown by both functional and genetic data, might result in prothrombotic and pro-inflammatory conditions, which contribute to brain ischemia." (PMID 40217918, 2025).
cerebral malaria (5 papers, 2011 to 2021). A sequestration of Plasmodium falciparum in the brain, which can cause coma and/or seizures. "Association of six single nucleotide polymorphisms (SNPs) of the ADAMTS13 gene with cerebral malaria was examined in 708 Thai patients with P. falciparum malaria." (PMID 22168261, 2011). "In this study, a SNP of ADAMTS13, rs4962153, was found to be significantly associated with cerebral malaria in 708 Thai patients with P. falciparum malaria." (PMID 22168261, 2011). "This study reports a significant association of common ADAMTS13 polymorphism with protection against cerebral malaria in Thai patients with falciparum malaria." (PMID 22168261, 2011). "Indeed, recent works have linked the platelet-mediated clumping of infected erythrocytes in microvasculature during cerebral malaria with increased level of VWF in plasma caused by mutations in ADAMTS13 genes." (PMID 34868193, 2021). "Since this is the first study reporting the significant association of ADAMTS13 polymorphism with cerebral malaria, further independent studies are required to examine whether the present finding can be replicated." (PMID 22168261, 2011). "A better understanding of the regulation of platelet-decorated ULVWF strings by ADAMTS13 would provide new insights into the development of the treatment of cerebral malaria." (PMID 22168261, 2011). "It has been reported that plasma ADAMTS13 function is significantly reduced in cerebral malaria patients compared to healthy controls." (PMID 22168261, 2011). "The genetic association observed in the present study implies that the regulation of platelet-decorated ULVWF strings by ADAMTS13 may play a role in the development of cerebral malaria." (PMID 22168261, 2011). "The present findings support the hypothesis that the regulation of platelet-decorated ULVWF strings by ADAMTS13 may play a role in the development of cerebral malaria." (PMID 22168261, 2011). "Recent studies reported increased levels of von Willebrand factor (VWF) and reduced activity of VWF-cleaving protease, ADAMTS13 (a disintegrin and metalloproteinase with a thrombospondin type 1 motif, member 13), in patients with cerebral malaria." (PMID 22168261, 2011).
cerebrovascular disease (5 papers, 2017 to 2025). "This is aimed at restoring ADAMTS13 activity to optimise vascular integrity to potentially retard the rate of sub-clinical cerebrovascular disease." (PMID 39274365, 2024). "This pattern of early cerebrovascular disease has also been reported in cTTP, suggesting that TTP or ADAMTS13 deficiency is characterized by a phenotype of accelerated vascular aging." (PMID 37762903, 2023).
chronic kidney disease (5 papers, 2010 to 2024). Impairment of the renal function secondary to chronic kidney damage persisting for three or more months. "The inverse covariation of vWF with ADAMTS-13 has been considered a prothrombotic state in chronic kidney disease." (PMID 34572522, 2021). "ADAMTS13 inhibited oxidative stress and ameliorated progressive chronic kidney disease after ischemia/reperfusion injury." (PMID 34666603, 2021). "Studies have shown that ADAMTS-13 can inhibit oxidative stress and improve the progression of chronic kidney disease after ischemia/reperfusion injury, while rhADAMTS-13 can inhibit ROS level, improve microvascular dysfunction, inhibit GSK3β activity and upregulate the expression of Nrf2." (PMID 34666603, 2021). "Importantly, in our study, patients with detectable ADAMTS13 activity had a frequent evolution to end-stage renal disease, similar to patients with HUS." (PMID 20436664, 2010).
dementia (5 papers, 2018 to 2025). Loss of intellectual abilities interfering with an individual's social and occupational functions. "Low ADAMTS13 activity was associated with an increased risk of dementia, with similar effect estimates throughout follow-up." (PMID 29615758, 2018). "We aimed to determine the cross-sectional and long-term associations of VWF and ADAMTS13 with cognitive decline and dementia risk in a population-based study." (PMID 29615758, 2018). "In conclusion, higher VWF and low ADAMTS13 activity are associated with accelerated cognitive decline and increased risk of dementia." (PMID 29615758, 2018). "The associations of VWF with cognitive decline and risk of dementia were not affected by concurrent ADAMTS13 activity (P-value for the interaction VWF*ADAMTS13 = 0.58 for all-cause dementia and and 0.85 the G-factor)." (PMID 29615758, 2018). "Associations of VWF and ADAMTS13 with dementia were mildly attenuated for Alzheimer’s disease only, and broadly unaltered by excluding participants with cardiovascular disease." (PMID 29615758, 2018). "Also, Wolters and colleagues reported an association between low ADAMTS13 activity and increased risk of dementia." (PMID 40969184, 2025). "Cardiovascular health is an important determinant of cognitive decline, but the association of either VWF or ADAMTS13 with risk of dementia is unknown." (PMID 29615758, 2018). "Along with the effect estimates for ADAMTS13 generally exceeding those of the ADAMTS13:VWF ratio, this renders it unlikely that proteolytic effects of ADAMTS13 on VWF alone are accountable for the association of ADAMTS13 with dementia." (PMID 29615758, 2018). "In conclusion, higher VWF and low ADAMTS13 activity are associated with increased risk of dementia, but differences in time-course and lack of synergistic effects may indicate in part independent underlying mechanisms." (PMID 29615758, 2018). "However, associations with VWF are restricted to short-term risks, and do not display synergistic effects with ADAMTS13 on dementia risk." (PMID 29615758, 2018). "Bolstering our confidence in our results using our given sample sizes and clinical diagnoses, another group came to the same conclusion about the presence of an imbalanced VWF/ADAMTS13 axis using a larger group of AD as well as non-AD dementia patients." (PMID 33946285, 2021). "Participants with dementia had higher VWF antigen levels and lower ADAMTS13 activity than individuals without dementia." (PMID 29615758, 2018). "Consequently, the ADAMTS13:VWF ratio was also lower in individuals with dementia, although adjustment for ADAMTS13 did not change the estimates for VWF, and ADAMTS13 did not modify the association of VWF with dementia (P-interaction = 0.93)." (PMID 29615758, 2018). "However, the time-course of the association between VWF and dementia remains unknown, and although ADAMTS13 could aid in disentangling haemostatic effects from associations marking endothelial damage, no published studies about VWF and dementia took into account concurrent ADAMTS13 activity." (PMID 29615758, 2018).
hemophilia (5 papers, 2009 to 2024). Hemophilia is a genetic disorder characterized by spontaneous hemorrhage or prolonged bleeding due to factor VIII or IX deficiency. "When the equilibrium is upset, increased vWF levels and decreased ADAMTS13 activity cause significant platelet and vascular hemophilia factor aggregation formation that can obstruct small blood arteries and cause end-organ ischemia." (PMID 38758904, 2024).
Multiple Organ Failure (5 papers, 2013 to 2023). A progressive condition usually characterized by combined failure of several organs such as the lungs, liver, kidney, along with some clotting mechanisms, usually postinjury or postoperative. "• ADAMTS13 deficiency may decrease clearance of excessively released ULVWF multimers, leading to spontaneous microvascular platelet thrombi formation and multiple organ failure." (PMID 24238574, 2013).
type 2 diabetes mellitus (5 papers, 2015 to 2025). A type of diabetes mellitus that is characterized by insulin resistance or desensitization and increased blood glucose levels. "ADAMTS13 activity appears to be an independent risk factor for incident prediabetes and type 2 diabetes." (PMID 27787621, 2017). "In this study, we examined whether ADAMTS13 activity or VWF antigen levels are associated with risk of type 2 diabetes in a large prospective population-based cohort study." (PMID 27787621, 2017). "As such, the observed association between ADAMTS13 activity and incident type 2 diabetes might be explained by the interaction of ADAMTS13 with one or more currently unknown proteins." (PMID 27787621, 2017). "We previously showed that type 2 diabetes patients have higher ADAMTS13 activity compared with controls, which is inconsistent with a mechanism involving VWF’s prothrombotic function." (PMID 27787621, 2017). "In other studies, the ADAMTS13 activity was higher in patients with type 2 diabetes." (PMID 36574434, 2022). "For example, there is preliminary evidence that ADAMTS13 upregulates vascular endothelial growth factor, a protein involved in angiogenesis that may contribute to the development of type 2 diabetes." (PMID 27787621, 2017). "ADAMTS13 may similarly activate other pathways that lead to the development of type 2 diabetes." (PMID 27787621, 2017).
acute liver failure (4 papers, 2019 to 2025). Rapid deterioration of liver function causing encephalopathy and coagulopathy. "Recently, the involvement of von Willebrand factor/ADAMTS13 has been suggested in thrombotic complications in liver transplantation patients, as well as a role for platelet-induced microthrombus formation in acute liver failure patients." (PMID 31717891, 2019). "In addition, given the profound decrease in ADAMTS13 levels and specific activity, we surmise the existence of backup mechanisms to control VWF reactivity in patients with acute liver failure and advanced chronic liver disease as we and others previously proposed." (PMID 41035784, 2025).
alcoholic hepatitis (4 papers, 2011 to 2023). Acute hepatitis resulting from ingestion of alcohol. "Furthermore, patients with ALF and severe alcoholic hepatitis with a significant imbalance in the ADAMTS13 enzyme–VWF substrate had a higher mortality risk than those without the imbalance as well as LC." (PMID 36829443, 2023). "A previous study reported that the VWF:Ag/ADAMTS13:AC in patients with severe alcoholic hepatitis was recovered in the recovery stage and worsened in the end stage compared with patients at the start of the treatment." (PMID 36829443, 2023). "In patients with alcoholic hepatitis, especially in severe cases complicated by LC, ADAMTS13 : AC concomitantly decreased, and VWF : Ag progressively increased with increasing concentrations of these cytokines from normal range to over 100 pg/mL." (PMID 21994870, 2011). "In patients with severe alcoholic hepatitis with or without cirrhosis, a negative association between ADAMTS-13, prothrombin time, and total serum bilirubin was observed, while VWF serum level was directly associated with disease severity." (PMID 37443746, 2023). "ADAMTS13 : AC significantly decreased in patients with hepatic veno-occlusive disease (VOD), alcoholic hepatitis, liver cirrhosis, and those undergoing living-donor-related liver transplantation and partial hepatectomy." (PMID 21994870, 2011).
bleeding disorder (4 papers, 2018 to 2023). "Regional domain mutation of VWF, on the other hand, increases proteolytic susceptibility to ADAMTS‐13, causing a bleeding disorder, type 2A von Willebrand disease (VWD)." (PMID 29108103, 2018). "ADAMTS13 (a disintegrin-like and metalloproteinase with thrombospondin type-1 motif 13)-related bleeding disorder has been frequently observed as a life-threatening clinical complication in patients carrying a circulatory assist device." (PMID 34785706, 2021). "A10/16E8 has potential application in the treatment of ADAMTS13-related bleeding disorder in patients undergoing mechanical circulatory assist device support." (PMID 34785706, 2021). "In this study, we constructed humanized A10 antibodies by CDR grafting with two human antibody frameworks, 8A7 and 16E816, to develop an applicable therapeutic agent for the treatment of patients with ADAMTS13-related bleeding disorder." (PMID 34785706, 2021). "A10/16E8 has great potential as a therapeutic agent for ADAMTS13-related bleeding disorder." (PMID 34785706, 2021).
breast carcinoma (4 papers, 2021 to 2025). "This is a unique report of TMA correlated with a non-invasive cystic pancreatic mucinous tumour, as well as the first report of breast cancer-associated TMA with the presence of an inhibitor of ADAMTS13." (PMID 40217615, 2025). "ADAMTS12 enhances tumor cell migration in PDAC, while ADAMTS15 increases cellular motility without affecting proliferation in breast cancer, paralleling the lack of a proliferative effect observed for ADAMTS13 in our study." (PMID 41211185, 2025).
Cognitive impairment (4 papers, 2020 to 2025). Abnormal cognition is characterized by deficits in thinking, reasoning, or remembering. "Notably, virus-mediated injection of ADAMTS13 into the hippocampi of APPPS1 mice with vascular damage, plaque deposition, and cognitive deficits beneficially reversed a diverse array of ADAMTS13 deficiency-related phenotypes, including cognitive impairment." (PMID 32183348, 2020).
endometriosis (4 papers, 2023 to 2025). The growth of functional endometrial tissue in anatomic sites outside the uterine body. "Another MR study has demonstrated the causal associations between ADAMTS13/vWF and the risk of endometriosis, suggesting the involvement of coagulation factors in endometriosis development." (PMID 38627726, 2024). "Our MR analysis based on GWAS data from large-scale population studies demonstrated the causal associations between ADAMTS13/vWF and the risk of endometriosis." (PMID 37226166, 2023). "In conclusion, our FinnGen cohort results suggest that ADAMTS13 levels are causally associated with a decreased risk of endometriosis, and the positive association observed between vWF and the risk of endometriosis is likely to be causal." (PMID 37226166, 2023). "The results supported the strong causal effect of ADAMTS13 on the decreased risk of endometriosis (IVW: OR = 0.42, 95%CI: 0.30–0.58, P = 2.85e − 7; WM: OR = 0.44, 95%CI: 0.30–0.66, P = 5.76e − 5)." (PMID 37226166, 2023). "The findings convincingly support the causal associations between ADAMTS13/vWF and the risk of endometriosis." (PMID 37226166, 2023). "The findings demonstrated that the genetically predicted plasma ADAMTS13 level is causally associated with a decreased risk of endometriosis (IVW: OR = 0.37, 95%CI: 0.22–0.61, P = 1.25e − 4; WM: OR = 0.41, 95%CI: 0.23–0.72, P = 2.05e − 3)." (PMID 37226166, 2023). "In other words, ADAMTS13 is found to have a protective effect associated with endometriosis, while vWF is characterized as a risk factor for the development of the condition." (PMID 37226166, 2023). "Our two-sample MR analysis of 11 coagulation factors in the UK Biobank suggested a reliable causal effect of genetically predicted plasma ADAMTS13 level on decreased endometriosis risk." (PMID 37226166, 2023). "Our findings of this MR study confirmed the causal roles of ADAMTS13 and vWF on endometriosis." (PMID 37226166, 2023). "In addition, the consistent causal effect estimates of ADAMTS13 on endometriosis among the UK Biobank, FinnGen, and the meta-analysis alleviated concerns on false-positive results." (PMID 37226166, 2023). "Our results indicate that genetically predicted plasma ADAMTS13 levels were inversely associated with endometriosis, while genetically predicted plasma vWF levels demonstrated a positive causal association with endometriosis, as confirmed in the meta-analysis combining the cohorts." (PMID 37226166, 2023). "For example, the findings underscore the significance of monitoring the ADAMTS13 plasma levels in individuals diagnosed with endometriosis." (PMID 37226166, 2023). "In particular, plasma levels of ADAMTS13 have been identified as a potential protective factor against endometriosis, highlighting the critical role of chronic inflammation in the pathophysiology of endometriosis." (PMID 41195131, 2025). "The result from random effects IVW analysis confirmed the strong negative causal link between ADAMTS13 and endometriosis." (PMID 37226166, 2023). "The findings highlighted that the plasma ADAMTS13 levels have a negative causal effect on endometriosis, whereas the plasma vWF levels have a positive causal effect on endometriosis." (PMID 37226166, 2023). "Furthermore, the results also provide a potential therapeutic approach that entails regulating the ADAMTS13 plasma level, thereby enabling the management and prevention of endometriosis progression and recurrence." (PMID 37226166, 2023). "A negative causal effect of ADAMTS13 and a positive causal effect of vWF on endometriosis were observed in the FinnGen." (PMID 37226166, 2023). "Notably, after accounting for multiple comparisons across 11 coagulation factors, the negative causal effects of plasma ADAMTS13 level on endometriosis remained significant (IVW: Padjusted = 1.38e − 3)." (PMID 37226166, 2023).
endometriosis (continued). "Summarizing the findings from the meta-analysis, we could conclude that the genetically predicted plasma ADAMTS13 levels have a negative causal effect on the risk of endometriosis, suggesting that ADAMTS13 serves as a protective factor for endometriosis." (PMID 37226166, 2023). "Through the Steiger test of directionality, the results corroborated the negative causal effects of ADAMTS13 and FXI on the risk of endometriosis." (PMID 37226166, 2023).